HDAC6 (histone deacetylase 6)
Diseases named in the same sentence as HDAC6 in open-access papers (continued):
Sharing a sentence is not in itself a finding about the gene and the disease.
Arthritis (11 papers, 2016 to 2024). Inflammation of a joint. "Present study showed that the mean arthritis score, number of swollen joints and paw thickness were significantly lower in HDAC6 shRNA-treated mice than in PBS-treated CIA mice." (PMID 38576491, 2024). "The arthritis score, arthritis swelling number and paw thickness were used to initially assess the role of HDAC6 shRNA in alleviating clinical disease in CIA mice." (PMID 38576491, 2024). "By confirming the protection of cartilage this work supports the inhibition of HDAC6 as a possible therapeutic strategy in arthritis." (PMID 35459919, 2022). "We and others showed that HDAC6 inhibitors suppress the inflammatory response of immune cells and ameliorate arthritis in a murine RA model." (PMID 34225810, 2021). "The HDAC6 inhibitor improved weight and reduced the clinical arthritis score in a dose-dependent manner." (PMID 34225810, 2021). "In conclusion, CKD-506, a novel HDAC6 inhibitor, regulates innate and adaptive immune responses and ameliorates experimental arthritis." (PMID 32711562, 2020). "We investigated the anti-arthritic effects of CKD-506, a novel HDAC6 inhibitor, in vitro and in a murine model of arthritis as a novel treatment option for rheumatoid arthritis (RA)." (PMID 32711562, 2020). "This was confirmed in an arthritis mouse model were HDAC6 inhibition resulted in decreased arthritis scores in mice." (PMID 30792714, 2019). "Our data demonstrated that CKD-L, a selective HDAC6 inhibitor, decreased the arthritis score and protected against joint destruction in the CIA model, and reduced the expressions of TNF and IL-1β, and increased the expression of IL-10 in PBMC from RA patients." (PMID 28673326, 2017). "CKD-L, a selective HDAC6 inhibitor, decreased the arthritis score in CIA, reduced the expression of TNF and IL-1β, and increased the expression of IL-10 in PBMC from RA patients." (PMID 28673326, 2017). "Therefore, we used pathological staining to observe the effect of HDAC6 shRNA on arthritis in CIA mice." (PMID 38576491, 2024). "Finally, the impact of HDAC6 inhibition on the severity of arthritis and joint histology was examined in a murine model of adjuvant-induced arthritis (AIA)." (PMID 34225810, 2021). "Finally, HDAC6 inhibitor M808 ameliorated clinical arthritis in an AIA-murine arthritis model in a dose-dependent manner." (PMID 34225810, 2021). "Due to the observation that HDAC6 inhibition in Treg cells resulted in enhanced suppressive function and a decrease in arthritis development in a mouse model, there is great interest in the potential application of specific HDAC6i immune suppression therapy in for example transplant recipients." (PMID 30792714, 2019). "HDAC6 shRNA significantly reduced the clinical signs of arthritis in CIA mice, as did the expression of HDAC6 in the serum and ankle synovial tissues of CIA mice." (PMID 38576491, 2024). "Treatment was started on Day 30 after the first immunization, and the model group continued to develop arthritis, same as previous studies; the arthritis severity scores of CIA mice injected with HDAC6 shRNA were notably lower than those of the other groups." (PMID 38576491, 2024). "For example, in the CIA mouse model and RA patients, the HDAC6 selective inhibitor, CKD-L, inhibits IL-6, TNF-α, and IL-1β expression, and increases IL-10 production, resulting in a decreased arthritis score and inhibited proliferation of effector T cells." (PMID 35453416, 2022). "Inhibiting HDAC6 dampens the inflammatory and destructive activity of RA-FLS and reduces the severity of arthritis." (PMID 34225810, 2021). "The novel HDAC6 inhibitor CKD-506 suppresses inflammatory responses by monocytes/macrophages, improves Treg function, and ameliorates arthritis severity in a murine model of RA." (PMID 32711562, 2020).
Arthritis (continued). "We show that inhibiting HDAC6 with CKD-506 improves Treg function, suppresses inflammatory responses by macrophages and FLS, and attenuates arthritis in a murine model of adjuvant-induced arthritis (AIA)." (PMID 32711562, 2020). "HDAC6 inhibitor, CKD-L decreased the arthritis score in collagen-induced arthritis model and reduced the expression of TNF-α and IL-1β in rheumatoid arthritis patients." (PMID 30841513, 2019). "In addition, the novel HDAC6 inhibitor, CKD-506, suppresses inflammatory responses by monocytes/macrophages, improves the function of regulatory T cells, and ameliorates arthritis severity in AIA rats." (PMID 35453416, 2022). "To date, few studies have shown the efficacy of HDAC6 inhibitors in arthritis models in vivo, however, the effects are likely not related to the HDAC6 function in protein turnover." (PMID 27623077, 2016).
cardiac hypertrophy (11 papers, 2016 to 2025). "Studies have shown that knockout of the HDAC5 and HDAC6 genes can block the COX2/PGE2 pathway in response to Ang II-induced cardiac hypertrophy." (PMID 40710369, 2025). "In summary, Ang II can induce cardiac hypertrophy by triggering an HDAC5/HDAC6-dependent mechanism that can be reversed by NaB." (PMID 40710369, 2025). "In conclusion, our study found that HDAC6 inhibition by TYA-018 reverses existing cardiac hypertrophy and diastolic dysfunction in multiple models of HFpEF, including the newly developed HFD+mTAC mouse model." (PMID 38409164, 2024). "Activation of Class I HDACs (HDACs 1, 2, 3, and 8) and Class IIb HDACs (HDAC6) are thought to promote pathological hypertrophy, whereas class II HDACs (HDACs 4, 5, 7, and 9) are thought to suppress cardiac hypertrophy." (PMID 36763506, 2023). "Class I HDACs (HDACs 1, 2, 3, and 8) and Class IIb HDAC (HDAC6) promote pathological hypertrophy, whereas Class IIa HDACs (HDACs 4, 5, 7, and 9) suppress cardiac hypertrophy." (PMID 36763506, 2023). "The production of ANP showed the similar pattern as that of COX2, which further suggested that inhibition of HDAC5 and HDAC6 protects cardiomyocytes from Ang II‐induced cardiac hypertrophy." (PMID 31565858, 2019). "In conclusion, we demonstrated that NaBu suppresses Ang II‐induced cardiac hypertrophy through the inhibition of COX2/PGE2 pathway in a HDAC5/HDAC6‐dependent manner." (PMID 31565858, 2019). "Previous studies have shown that HDAC6 is involved in cardiac hypertrophy and may also be involved in heart failure." (PMID 40710369, 2025). "In HFD + L-NAME mice, the expression of HDAC6 protein was also increased, correlated with the upregulation of Nppb and Col3a1, and severity of diastolic dysfunction [based on the early diastolic velocity ratio (E/e’)] and cardiac hypertrophy (based on LVPWd)." (PMID 38409164, 2024). "Specially, a study demonstrates that sodium butyrate may function to inhibit HDAC5/HDAC6 to attenuate angiotensin (Ang) II-induced cardiac hypertrophy, suggesting HDAC5 may be a therapeutic target of cardiac hypertrophy." (PMID 37667300, 2023). "Taken together, these results demonstrated that NaBu may suppress Ang II‐induced cardiac hypertrophy through COX2 signalling pathway by inhibiting the activation of HDAC5/HDAC6." (PMID 31565858, 2019). "To further confirm the regulation of class II HDACs (HDAC5 and HDAC6) on the expression of COX2 and Ang II‐induced cardiac hypertrophy, we performed expression knockdown of HDAC5 and HDAC6 genes in H9C2 cells via CRISPR/Cas9 gene‐editing plasmids." (PMID 31565858, 2019). "Thus, miR-1 is one of the crucial regulators of pathological cardiac hypertrophy by fine-tuning the translation of different molecules, including eukaryotic initiation factor 4E (EIF4E), Mef2a, Gata4 and histone deacetylase 6 (HDAC6)." (PMID 33371511, 2020). "To further confirm that NaBu may protect against Ang II‐induced cardiac hypertrophy through inhibition of HDAC5 and HDAC6, we carried out gene knockdown of HDAC5 and HDAC6 in cultured H9C2 cells via CRISPR/Cas9 strategy." (PMID 31565858, 2019).
depression (11 papers, 2012 to 2026). "The inhibition of HDAC6 causes a reduction in cortical-spreading depression and a block of the CGRP receptor." (PMID 40711166, 2025). "Altogether, though purely speculative, these data suggest a role for HDAC6 in mediating the association between prenatal maternal infection and the development of depression in the offspring." (PMID 27216537, 2016). "FST is commonly used to detect depression in animals; our findings suggest that the effect of HDAC6 deficiency on depression in animals was subtle, which is in agreement with the result of a tail suspension test (TST) in neuron-specific Hdac6 knockout mice." (PMID 37373121, 2023). "Our date with depression reversal are consistent with those findings suggesting that neurological effects of Hdac6 are age dependent." (PMID 33004910, 2020). "To obtain insight into the mechanism of emotional abnormalities of Hdac6 KO mice, we focused on the alteration in the content of serotonin, an important factor of etiology of depression." (PMID 22328923, 2012). "Our findings also suggest that HDAC6-mediated reversible acetylation can become a new therapeutic target for depression." (PMID 22328923, 2012). "This work illuminates the molecular relationship between depression and neuroinflammation while establishing [18F]PB200 as a valuable tool for evaluating HDAC6-targeted therapeutic interventions, potentially advancing precision diagnosis and treatment approaches for depression." (PMID 41547180, 2026). "HDAC6 knockout can effectively reverse the phenotype for depression in mice." (PMID 35449808, 2022). "Moreover, previous rodent model studies aimed at investigating mood disorders and depression have confirmed the elevation of HDAC6 gene expression, whereas HDAC6 inhibitors have been shown to be effective as antidepressants and mood stabilizers." (PMID 34115777, 2021). "Inflammation has been correlated with depression in a number of studies, therefore, alleviating inflammatory signaling may be a mode of action of Hdac6 depletion." (PMID 33004910, 2020). "Since stress is considered to be one of the important contributors in the etiology of depression, we investigated whether stress state and/or stress response is affected in Hdac6 KO mice." (PMID 22328923, 2012).
neuropathy (11 papers, 2014 to 2025). A disorder affecting the nervous system that manifests with pain, tingling, numbness, and/or muscle weakness. "This study evaluates the HDAC6 inhibitor ITF6475 for its potential to prevent PIPN and compares its effects with ricolinostat, a well-established HDAC6 inhibitor previously studied in cisplatin-induced neuropathy models." (PMID 41012388, 2025). "The alignment between pharmacological and genetic evidence provides strong support for HDAC6’s role in certain neuropathies." (PMID 41012388, 2025). "Although the precise mechanism by which HDAC6 inhibition mitigates neuropathy is not fully understood, evidence suggests that this enzyme plays a crucial role in mitochondrial trafficking and energy metabolism." (PMID 41012388, 2025). "Since HDAC6 plays a role in regulating immune response, in the development of neuropathies and in Alzheimer’s disease, the identification of highly specific HDAC6is is of great importance." (PMID 36528061, 2023). "The inhibition of HDAC6 has been reported to ameliorate the severity of inherited neuropathy in animal models—such as Charcot–Marie–Tooth type 2—indicating, such a possible role of acetylation and HDAC6 in the onset of neuropathies." (PMID 31075828, 2019). "We have previously demonstrated that the same regimen of HDAC6 inhibition resolves cisplatin-induced neuropathy." (PMID 30270813, 2018). "Interestingly, in a reverse mouse study, neuropathy was also detected and was attenuated by co-administrations of a HDAC6 inhibitor." (PMID 38897995, 2024). "Our findings open the way for the development of novel HDAC6 selective inhibitors for the treatment of neuropathies and other diseases, but they also point to the intriguing possibility to use oxadiazoles in the development of selective inhibitors of other HDAC subtypes." (PMID 36528061, 2023). "Treatment with Tubastatin A (TubA), an inhibitor of histone deacetylase 6 enzyme (HDAC6) previously shown to confer protection in mutant HSPB1-induced neuropathy, increased the levels of acetylated tubulin and restored the normal axonal transport of these organelles in Gan−/−DRG neurons." (PMID 37268847, 2023). "Histone deacetylase 6 (HDAC6) is an attractive drug development target because of its role in the immune response, neuropathy, and cancer." (PMID 36528061, 2023). "The development of transgenic mouse models of mutant HSPB1 neuropathy and the encouraging preclinical studies of HDAC6 inhibitors in HSPB1 and GARS neuropathy have highlighted the need for robust natural history with which to guide future trial design." (PMID 27816334, 2017). "Examples are treatment with HDAC6 inhibitors in HSPB1 mutant mice, restoring axonal transport defects, and treatment with curcumin improving outcome of neuropathy in MPZ mutant mice." (PMID 25025039, 2014).
osteosarcoma (11 papers, 2015 to 2025). A usually aggressive malignant bone-forming mesenchymal neoplasm, predominantly affecting adolescents and young adults. "In our study, we verified the anti-osteosarcoma effect of the selective HDAC6 inhibitor ISOX through ER stress-related signature screening." (PMID 38229155, 2024). "The pharmacological or genetic abrogation of HDAC6 in osteosarcoma cell lines decreased PD-L1 expression, which activated the inhibitory regulatory pathway of PD-1 expression in T cells." (PMID 36076996, 2022). "WT-161, an inhibitor of HDAC6, induced the apoptosis of osteosarcoma cells by increasing the expression of PTEN." (PMID 36076996, 2022). "In this report, we found that the K7 of Rab22a-NeoF1, acetylated by p300/CBP while de-acetylated by both HDAC6 and SIRT1, plays a key role in its binding to SmgGDS607, and consequently affects its activation of RhoA and promotion of cell migration, invasion and lung metastasis in osteosarcoma." (PMID 32685017, 2020).
renal fibrosis (11 papers, 2016 to 2026). A final common manifestation of a wide variety of chronic kidney diseases characterized by glomerulosclerosis and tubulointerstitial fibrosis. "HDAC6 is associated with the occurrence and development of a variety of diseases, including neurodegenerative diseases, cancer, cardiovascular diseases, renal fibrosis, cystogenesis, and inflammation." (PMID 38317159, 2024). "In vivo and in vitro experiments showed the suppressive effect of HDAC6 suppression on renal fibrosis and inflammation can be abolished by KLF5 overexpression." (PMID 39412062, 2024). "Overall, HDAC6 aggravated renal fibrosis and inflammation in mice with LN via the MAFF/KLF5 signaling axis." (PMID 39412062, 2024). "CAY10603 (a specific inhibitor of HDAC6) attenuates renal fibrosis in DKD by inhibiting NLRP3 inflammasome activity in RTCs and macrophages." (PMID 38929505, 2024). "This study explored the effect and mechanism of MAFF and HDAC6 on renal fibrosis and inflammation in lupus nephritis (LN)." (PMID 39412062, 2024). "Nevertheless, the mechanism by which HDAC6 mediates renal fibrosis in LN remains much to be determined." (PMID 39412062, 2024). "In mouse renal fibrosis models, suppression of HDAC6 expression led to suppressed fibroblast activation and extracellular matrix (ECM) deposition by blocking α-smooth muscle actin (α-SMA), collagen type III, and fibronectin expressions." (PMID 39412062, 2024). "Our recent studies have shown that blockade of HDAC6 with ACY-1215 also attenuated renal fibrosis through a mechanism involving the inactivation of TGFβ1/Smad3, EGFR/AKT, STAT3 and NF-κB signaling pathways in a murine model of UUO injury." (PMID 35559244, 2022). "Since HADC4 is one of class IIa HDAC isoforms, we have recently examined the role and mechanisms of class IIa HDACs and HDAC6 in the development of renal fibrosis following UUO injury." (PMID 35559244, 2022). "A study showed that the expression of HDAC6 was increased in a mouse model of renal fibrosis, treatment with HDAC6 selective inhibitor or small interfering RNA against HDAC6 attenuated the renal fibrosis." (PMID 33896334, 2021). "Our recent study demonstrated that HDAC6 contribute to fibrosis by direct activation of renal interstitial fibroblast, HDAC6 involve in renal fibrosis by the activation of TGF-β1/Smad3 and EGFR signaling pathways in UUO model." (PMID 33896334, 2021). "For instance, renal fibrosis can be attenuated by reducing autophagy through HDAC6 reduction and microtubule disruption." (PMID 32985730, 2020). "HDAC6 contributes to renal fibrosis through regulation of epigenetic histone modification and Smad3-dependent fibrotic genes." (PMID 30134806, 2018). "A previous study showed that the expression of HDAC6 was increased in a hypertensive kidney damage mouse model, and inhibition of HDAC6 or small interfering RNA against HDAC6 attenuated hypertensive stimuli-induced renal fibrosis and inflammation." (PMID 30134806, 2018). "Recent studies have demonstrated that HDAC6 inhibition can improve polycystic kidney disease, renal fibrosis and acute kidney injury in animal models." (PMID 29179471, 2017). "ACY-1215 (a selective HDAC6 inhibitor) could reduce renal fibrosis by inhibiting pro-fibrotic pathways (TGF-β/SMAD3, EGFR), myofibroblast activation, and inflammation." (PMID 38929505, 2024). "All evidences supported the regulation of HDAC6 on renal fibrosis in LN." (PMID 39412062, 2024). "This study explored the possible effect and involvement of HDAC6 in regulating renal fibrosis and inflammation in LN using both in vivo and in vitro experiments and highlighted the promotive effect of HDAC6 on LN progression through regulating the MAFF/KLF5 axis." (PMID 39412062, 2024).
renal fibrosis (continued). "In this study, we explored the role of the HDAC6/MAFF/KLF5 axis in renal fibrosis and inflammation using both in vivo and in vitro experiments with the expectation to provide a theoretical basis for proposing new treatment approaches for LN patients, especially for pediatric patients." (PMID 39412062, 2024). "Previous studies demonstrated that HDAC6 involved in renal fibrosis in animal models." (PMID 33896334, 2021). "Recently, we reported that tubastatin A, an HDAC6‐selective inhibitor, suppresses renal fibrosis." (PMID 27420561, 2016). "However, our present study is a cross-sectional project, whether the HDAC6 could induce renal fibrosis in IgAN then lead to the renal dysfunction is still unknown." (PMID 33896334, 2021). "Numerous studies have recently demonstrated that HDAC6 expression and activity are increased in kidney disease, such as autosomal dominant polycystic kidney disease (ADPKD), renal fibrosis, and acute kidney injury (AKI), among others." (PMID 30134806, 2018). "Hence, HDAC6 may be a valuable therapeutic target for the treatment of renal fibrosis." (PMID 30134806, 2018). "Our findings are supported by several studies showing that renal fibrosis was attenuated by the pan-HDAC inhibitor TSA, class I HDAC inhibitor MS-275, and HDAC6-selective inhibitor Tubastatin A." (PMID 27902771, 2016). "Taken together, our data shed light on the epigenetic side of renal fibrosis and provide evidence that the epigenetic interaction between ATF3 and HDAC6 might be a promising target for kidney fibrosis." (PMID 41522362, 2026). "Considering the finding of our previous study that KLF5 promotes renal fibrosis in MRL/lpr mice, it is reasonable to speculate the possible effect of HDAC6/MAFF/KLF5 axis in LN." (PMID 39412062, 2024). "Moreover, HDAC6 inhibitor Tubastatin A was found to suppress fibrosis and inflammation in hypertensive mice and attenuate renal tubular damage in acute kidney injury, this suggests that HDAC inhibition has beneficial effects in renal fibrosis." (PMID 39412062, 2024).